CSF1R (colony stimulating factor 1 receptor)
Diseases named in the same sentence as CSF1R in open-access papers (continued):
Sharing a sentence is not in itself a finding about the gene and the disease.
chronic hepatitis C (1 paper, 2021). "Another glycan marker for HCC, WFA+-colony stimulating factor 1 receptor (CSF1R), was identified from the analysis of sera from patients with chronic hepatitis C and cirrhosis." (PMID 34681709, 2021). "An analysis of sera from patients with chronic hepatitis C, cirrhosis and HCC showed that WFA+-CSF1R is potentially useful for predicting liver carcinogenesis and prognosis of cirrhosis." (PMID 34681709, 2021).
chronic lymphocytic thyroiditis (1 paper, 2022). "Moreover, CSF1 induces pro-tumoral M2 macrophage polarization through binding to CSF1R, whereas CXCL9 and CXCL10 are involved in T-cell recruitment manifested as chronic lymphocytic thyroiditis, which has been associated with a better prognosis of PTC." (PMID 35515000, 2022).
chronic myelomonocytic leukemia (1 paper, 2019). A myelodysplastic/myeloproliferative neoplasm which is characterized by persistent monocytosis, absence of a Philadelphia chromosome and BCR/ABL fusion gene, fewer than 20 percent blasts in the bone marrow and blood, myelodysplasia, and absence of PDGFRA or PDGFRB rearrangement. "CSF-1R expression and chromatin recruitment is modulated by small molecule CSF-1R inhibitors and altered in monocytes from chronic myelomonocytic leukemia patients." (PMID 31028249, 2019). "This function is affected by small molecule CSF-1R inhibitors and altered in dysplastic monocytes collected from chronic myelomonocytic leukemia (CMML) patients." (PMID 31028249, 2019).
colorectal tumors (1 paper, 2022). "Moreover, we demonstrated that CSF1R+ macrophages favored immune suppression mainly by limiting CD8+ T cell infiltration and differentiation, which is compatible with a previous study in CSF1-silenced colorectal tumors that presented increased CD8+ T cell attack." (PMID 35315360, 2022).
Dandy-Walker malformation (1 paper, 2023). "Compared to CSF1R-ALSP, cases with BANDDOS also displayed other congenital brain anomalies, including Dandy-Walker malformation, ventriculomegaly, and cortical abnormalities." (PMID 37349768, 2023).
delirium (1 paper, 2022). A disorder characterized by confusion; inattentiveness; disorientation; illusions; hallucinations; agitation; and in some instances autonomic nervous system overactivity. "LM‐ and AS‐induced delirium led to microglial activation in the hippocampus as evidenced by up‐regulation of microglial activation‐related genes (such as Il6ra, Tyrobp, Cd68, Aif1, Csf1r, and Trem2) and of relevant inflammatory factors (such as Il‐1β, Tnfα, Ccl2, Ccl5, and Ccl8)." (PMID 35713240, 2022).
diabetic foot ulcer (1 paper, 2025). "In diabetic foot ulcer, miR-361-3p expression is inversely correlated with CSF1R expression." (PMID 41446787, 2025).
diabetic kidney disease (1 paper, 2026). Progressive kidney disorder caused by vascular damage to the glomerular capillaries, in patients with diabetes mellitus. "DDIT3, GADD45A, THBS2, CCL2, and CSF1R showed consistent expression trends across platforms, and are known mediators of inflammation, extracellular matrix remodeling, and stress responses in diabetic kidney disease." (PMID 41481573, 2026).
Down syndrome (1 paper, 2023). "Depletion of microglia with PLX3397, a colony stimulating factor 1 receptor (CSF1R) inhibitor, recovers the cognitive performance in juvenile animals of the Dp mouse model of Down Syndrome." (PMID 37670386, 2023).
ductal carcinoma (1 paper, 2009). "Also, expression of oncoproteins with anti-apoptotic activities, including receptor tyrosine kinase ErbB2, colony-stimulating factor 1 receptor, SRC, and IGF1R, has been shown to elicit abnormal, filled phenotypes that resemble human ductal carcinoma in vivo." (PMID 20043854, 2009).
esophageal adenocarcinoma (1 paper, 2022). A malignant tumor with glandular differentiation arising predominantly from Barrett mucosa in the lower third of the esophagus. "From these data, we identified pathways related to the tumor immune microenvironment that were correlated with enriched TAM and overexpression of colony-stimulating factor 1 receptor (CSF-1R), indicating the potential role of these upregulated pathways in esophageal adenocarcinoma." (PMID 35455743, 2022).
esophageal cancer (1 paper, 2022). A primary or metastatic malignant neoplasm involving the esophagus. "In the present study, our analysis of the TCGA dataset showed for the first time that there is also a high enrichment of CSF-1R and macrophages in esophageal cancer." (PMID 35455743, 2022). "However, it is notable that the observed high level of CSF-1R, which is an important receptor for shifting macrophages toward the M2 phenotype, may suggest the importance of M2 macrophages in esophageal cancer tumorigenesis." (PMID 35455743, 2022).
glaucoma (1 paper, 2023). Increased pressure in the eyeball due to obstruction of the outflow of aqueous humor. "In contrast, microglia depletion studies using CSF1R blockers show increased RGC loss and progressive astrocytosis using the microbead-induced glaucoma model, suggesting a protective role for microglia in glaucoma, highlighting the complexity of the involvement of microglia in glaucoma." (PMID 36837806, 2023).
Glucose intolerance (1 paper, 2023). Glucose intolerance (GI) can be defined as dysglycemia that comprises both prediabetes and diabetes. "On the contrary, mouse models lacking major components of innate immunity by either genetic (CCR2-/- mice) or pharmacological manipulation (CSF1R-inhibition) were protected from DEP-induced gut inflammation and glucose intolerance." (PMID 37400850, 2023). "In sum, pharmacological macrophage depletion by the CSF1R-inhibitor PLX5622 protected mice from DEP-induced gut inflammation and glucose intolerance." (PMID 37400850, 2023).
HCMV infection (1 paper, 2020). "We have further identified an mRNA-binding protein that is induced by HCMV infection and directly inhibits the expression of CSF1-R." (PMID 31959222, 2020). "Recently, our laboratory discovered, in vitro, that HCMV infection is able to inhibit osteoclastogenesis through inhibition of CSF-1R expression, which prompted us to consider that HCMV could have an impact on joint destruction evolution during early RA, and more particularly on bone erosion." (PMID 31959222, 2020).
Hereditary Diffuse Leukoencephalopathy with Spheroids (1 paper, 2022). "CSF1R mutations have been associated with Hereditary Diffuse Leukoencephalopathy with Spheroids (HDLS) [MIM: 221820] A postmortem brain tissue examination supported HDLS diagnosis for the CSF1R c.2068G>A (p.Gly690Ser) variant carrier." (PMID 35260199, 2022).
histiocytic neoplasm (1 paper, 2025). Histiocytic tumors are a heterogeneous group of tumors and tumorlike masses commonly associated with histologically identical extracranial lesions. "Activating mutations in the CSF1R, encoding the colony-stimulating factor 1 receptor, have been identified in histiocytic neoplasms, suggesting a role in disease development and potential therapeutic targeting." (PMID 39998733, 2025).
hypoxia (1 paper, 2021). A decrease in the amount of oxygen in the body. "Our results suggest that CSF1R inhibition suppresses neuroinflammation and neonatal brain injury after acute cerebral hypoxia-ischemia in neonatal mice." (PMID 33679579, 2021).
hypoxic-ischemic encephalopathy (1 paper, 2022). "Activation of Csf1r/Plcg2 signaling pathway attenuates inflammation and thus regulates the pathogenesis of hypoxic-ischemic encephalopathy." (PMID 35346355, 2022).
Impaired glucose tolerance (1 paper, 2023). An abnormal resistance to glucose, i.e., a reduction in the ability to maintain glucose levels in the blood stream within normal limits following oral or intravenous administration of glucose. "The discordant behaviour of impaired glucose tolerance alongside improved insulin sensitivity in PLX5622-treated mice suggested that CSF1R inhibition affected beta cell function." (PMID 37792013, 2023). "Hence, CSF1R inhibition by PLX5622 led to a discordant behaviour of impaired glucose tolerance but improved insulin sensitivity." (PMID 37792013, 2023).
ischemic disease (1 paper, 2022). Lack of blood supply to an area of the body, resulting in impairment of tissue oxygenation. "It is possible that Csf1r/Plcg2 exerted the similar effects in MI that is also an ischemic disease." (PMID 35346355, 2022).
lower respiratory tract infections (1 paper, 2023). "The main enriched items for CSF1R were recurrent lower respiratory tract infections, viral hepatitis, and abnormal lymphocyte physiology." (PMID 37760894, 2023).
lymph node metastasis (1 paper, 2024). "Furthermore, higher CSF-1R expression was found to be significantly associated with patient tumor size, lymph node metastasis, and FIGO stage in this study, consistent with the literature." (PMID 38303927, 2024). "Additionally, data showed that high expression of CSF-1R was associated with lymph node metastasis." (PMID 38303927, 2024). "The results showed that patients in the high CSF-1R expression group had a higher proportion of tumor size, lymph node metastasis, and FIGO (International Federation of Obstetrics and Gynecology) stage than those in the low CSF-1R expression group." (PMID 38303927, 2024).
malignant mesothelioma (1 paper, 2016). A malignant neoplasm of the pleura or peritoneum, arising from mesothelial cells. "Thus, this work, together with our previous observations in malignant mesothelioma cell lines and primary specimens, points to an additional role for CSF-1R which complement its better characterized function at promoting development and survival of tumor-associated macrophages." (PMID 27486763, 2016).
mantle cell lymphoma (1 paper, 2022). Mantle cell lymphoma is a rare form of malignant non-Hodgkin lymphoma affecting B lymphocytes in the lymph nodes in a region called the ``mantle zone''. "Targeting CSF1R caused abrogation of CD163+ TAMs in mantle cell lymphoma (MCL), irrespective of the sensitivity to BTK inhibitors." (PMID 36578079, 2022).
mastitis (1 paper, 2024). Inflammation of breast tissue during lactation or postpartum due to an obstructed duct or infection. "The network analysis showed that the CSF1R, RHO, RCVRN, CAV3, and GATA4 genes were core nodes, suggesting that these genes could serve as candidate molecular markers for mastitis." (PMID 38674399, 2024). "Notably, the lncRNA-miRNA-mRNA ternary co-expression network of RHO, RCVRN, CSF1R, CAV3, and GATA4 genes is likely to be involved in the regulation of mastitis in Xinjiang brown cattle." (PMID 38674399, 2024).
memory impairment (1 paper, 2020). "In summary, we have shown that short-term memory impairment induced by prolonged Ang II infusion is partly prevented when microglia/PVM are depleted using a CSF1R inhibitor." (PMID 32863942, 2020). "It would be of interest to investigate if the blockade of astrocyte reactivity alone or in combination with CSF1R inhibition could fully prevent the short-term memory impairment induced by Ang II." (PMID 32863942, 2020).
Menstrual disorder (1 paper, 2016). Category of disorders related to menstruation. "The apparent divergence of CSF-1R-dependence amongst macrophages in the endometrium may provide a novel strategy for targeting endometrial macrophage subsets which may be a beneficial therapeutic target in the treatment of menstrual disorders." (PMID 27827431, 2016).
Metaphyseal dysplasia (1 paper, 2020). The presence of dysplastic regions in metaphyseal regions. "Homozygous mutations of the CSF1R gene cause a generalized increase in bone density and metaphyseal dysplasia by influencing osteoclasts, suggesting that CSF1R deficiency may have an additional role in skeletal abnormalities." (PMID 33287883, 2020).
metastasis (1 paper, 2025). The spread or migration of cancer cells from one part of the body (where they first appeared) to another. "To confirm the relevance of CSF-1R inhibition to TNBC, we tested the ability of BLZ945 to prevent and treat brain metastasis in a second hematogenous brain metastasis model system." (PMID 40760255, 2025).
motor neuron degeneration (1 paper, 2021). "This highly specific tyrosine kinase inhibitor blocks the CSF1R and c-Kit pathways, which means the activation of immune cells including mast cells and macrophages, also involved in motor neuron degeneration in SOD1G93A." (PMID 33810425, 2021).
myelodysplastic syndrome (1 paper, 2020). A clonal hematopoietic disorder characterized by dysplasia and ineffective hematopoiesis in one or more of the hematopoietic cell lines. "CSF1R inhibitor and anti-CD47 antibodies or anti-SIRPα antibodies have been applied for solid tumors and some hematologic malignancies such as acute myeloid leukemia and myelodysplastic syndrome (MDS)." (PMID 33644032, 2020).
myeloid malignancies (1 paper, 2012). "CSF1R codes for a cytokine that controls the monocyte-macrophage system and PDGFRB is involved in various myeloid malignancies." (PMID 22253721, 2012).
neutropenia (1 paper, 2019). A decrease in the number of neutrophils found in the blood. "Neutropenia is another common toxicity in our study, which could be related to the inhibition of Aurora B and CSF-1R kinases." (PMID 30642372, 2019).
ovarian carcinosarcoma (1 paper, 2026). A highly aggressive malignant neoplasm arising from the ovary. "Molecular analysis using next-generation sequencing identified PIK3CA H1047R (c.3140A > G) and CSF1R (c.∗1841TG > GA) in both the epithelial and mesenchymal components, indicating a clonal origin and supporting a diagnosis of primary ovarian carcinosarcoma." (PMID 42211942, 2026).
pancreatic (1 paper, 2021). "Antagonists of colony-stimulating factor 1 receptor (CSF1R) or of the chemokine receptor CCR2 substantially decreased the tumor-initiating properties of CSCs in pancreatic mouse tumor models." (PMID 34583655, 2021).
pancreatic neuroendocrine cancers (1 paper, 2013). "CSF-1/CSF-1R and CCL2 (MCP-1)/CCR2 signaling in murine breast and pancreatic neuroendocrine cancers induces TAM recruitment and a pro-tumorigenic M2-like phenotype." (PMID 23372702, 2013).
pancreatic neuroendocrine tumor (1 paper, 2024). Pancreatic endocrine tumor, also known as pancreatic neuroendocrine tumor (PNET), describes a group of endocrine tumors originating in the pancreas that are usually indolent and benign, but may have the potential to be malignant. "Surufatinib (Sulanda® in China) is an oral, small-molecule, anti-VEGFR kinase inhibitor that targets VEGFR-1, -2, and -3, FGFR-1, and colony-stimulating factor-1 receptor (CSF-1R) and was approved in China for the treatment of pancreatic and non-pancreatic neuroendocrine tumors." (PMID 39055564, 2024).
pleural tumor (1 paper, 2022). "CSF1R inhibitor administration limits MPE and pleural tumor dissemination by attenuating tumor angiogenesis and enhancing tumor cell apoptosis in vivo." (PMID 35315360, 2022).
primary progressive multiple sclerosis (1 paper, 2021). A multiple sclerosis that is characterized by steady worsening of neurologic functioning, without any distinct relapses or periods of remission. "Several motor predominant cases of ALSP caused by heterozygous CSF1R mutations has been reported to mimic primary progressive multiple sclerosis (PPMS)." (PMID 34867307, 2021).
schwannoma (1 paper, 2020). A benign, usually encapsulated slow growing tumor composed of Schwann cells. "We found that upregulated genes PIK3CG, CSF1R, SPP1, and CCND1 and downregulated genes EGFR and VWF were significantly enriched in PI3K-Akt signaling pathway involved in VSs development, which can increase schwannoma cell proliferation, survival, and cell-matrix adhesion acting." (PMID 32733557, 2020).
Sciatica (1 paper, 2025). Pain in the lower back and hip radiating in the distribution of the sciatic nerve. "The study also found that continued use of PLX5622, a specific colony-stimulating factor 1 receptor antagonist, reduced macrophages and microglia, thereby effectively alleviating LDH-induced sciatica." (PMID 40224631, 2025).
Seizure (1 paper, 2023). A seizure is an intermittent abnormality of nervous system physiology characterized by a transient occurrence of signs and/or symptoms due to abnormal excessive or synchronous neuronal activity in the brain. "Seizures were noted in 56% of cases in BANDDOS, compared to up to 32% of CSF1R-ALSP." (PMID 37349768, 2023).
skin squamous cell carcinoma (1 paper, 2023). A carcinoma arising from the squamous cells of the epidermis. "Antibody depletion of CSF1R+ macrophages in INHBA-driven skin squamous cell carcinoma delayed the onset of tumor growth and decreased tumor vascularization." (PMID 38304252, 2023).
systemic mastocytosis (1 paper, 2014). Systemic mastocytosis (SM) comprises a heterogeneous group of rare acquired and chronic hematological malignancies that are related to an abnormal proliferation of mast cells in tissue, including bone marrow, with or without skin involvement. "Whereas KIT D816V/H mutation is a well-characterized oncogenic event and principal cause of systemic mastocytosis, the homologous CSF-1R D802V has not been identified in human cancers." (PMID 24828813, 2014). "Actually, KIT D816V gain-of-function mutation is a well-characterized oncogenic event and identified in more than 80% of systemic mastocytosis, whereas the equivalent CSF-1R D802V mutation has not been found in human tumors." (PMID 24828813, 2014).
testicular germ cell tumor (1 paper, 2023). A germ cell tumor arising from the testis. "Furthermore, recent data indicates a correlation between AhR expression and immune inhibitors including colony-stimulating factor 1 receptor (CSF1R) and galectin 9 (LGALS9) in uterine carcinosarcoma and IL10RB in testicular germ cell tumors." (PMID 37241719, 2023).
Tinnitus (1 paper, 2019). Tinnitus is an auditory perception that can be described as the experience of sound, in the ear or in the head, in the absence of external acoustic stimulation. "To determine the contribution of microglia to noise-induced TNF-α expression and tinnitus, we eliminated a proportion of microglia with PLX3397, an inhibitor of colony-stimulating factor 1 receptor (CSF1R)." (PMID 31211773, 2019).
urinary system cancers (1 paper, 2023). "Except those frequent mutated genes in urinary system cancers, we also identified other less frequent mutated genes, including CSF1R (37%), NPM1 (37%), EGFR (25.9%), and NOTCH1 (22.2%)." (PMID 37515929, 2023).
vascular sarcoma (1 paper, 2014). A sarcoma arising from vascular tissue including arteries, veins, venous sinuses, arterioles and capillaries. "We identified drug sequestration within cellular lysosomes as a shared drug resistance mechanism in human and canine vascular sarcomas marked by high CSF-1R expression." (PMID 25295160, 2014).